CREB3L4 (cAMP responsive element binding protein 3 like 4)
Description:
Transcriptional activator that may play a role in the unfolded protein response. Binds to the UPR element (UPRE) but not to CRE element. Preferentially binds DNA with to the consensus sequence 5'-T[GT]ACGT[GA][GT]-3' and has transcriptional activation activity from UPRE. Binds to NF-kappa-B site and has transcriptional activation activity from NF-kappa-B-containing regulatory elements (By similarity).
Synonyms: AIbZIP; ATCE1; CREB4; JAL; CREB3; hJAL
Tractability: Antibody: UniProt predicts a signal peptide or a membrane-spanning region. PROTAC: ubiquitination databases record sites on it.
Gene: Protein-coding gene on chromosome 1 (153,963,719 to 153,974,364, forward strand). Ensembl gene ENSG00000143578.
Subcellular location: Endoplasmic reticulum membrane; Golgi apparatus membrane; Nucleus (Processed cyclic AMP-responsive element-binding protein 3-like protein 4)
Subcellular location (Human Protein Atlas): Nuclear membrane; Nucleoplasm; Mitochondria
Pathways (Reactome):
Cellular responses to stimuli: CREB3 factors activate genes
Gene Ontology:
Molecular function: protein binding; sequence-specific double-stranded DNA binding; DNA-binding transcription factor activity, RNA polymerase II-specific; RNA polymerase II cis-regulatory region sequence-specific DNA binding; DNA binding; DNA-binding transcription activator activity, RNA polymerase II-specific; DNA-binding transcription factor activity; RNA polymerase II transcription regulatory region sequence-specific DNA binding
Biological process: positive regulation of transcription by RNA polymerase II; regulation of transcription by RNA polymerase II; regulation of DNA-templated transcription
Cellular component: endoplasmic reticulum; Golgi apparatus; chromatin; nucleus; endoplasmic reticulum membrane; Golgi membrane
Genetic constraint (gnomAD): Loss-of-function variants: 28 observed, 39.03 expected, observed/expected ratio (o/e) 0.72, 90% interval 0.53 to 0.98. The upper end of that interval is the gene's LOEUF score, 0.98, which puts it in group 4 of 6, group 1 being the genes least tolerant of losing a copy. Missense variants: 462 observed, 509.96 expected, observed/expected ratio (o/e) 0.91, 90% interval 0.84 to 0.98. Synonymous variants: 175 observed, 203.48 expected, observed/expected ratio (o/e) 0.86, 90% interval 0.76 to 0.98.
Homologues: Orthologues: chimpanzee CREB3L4 (99% identical), macaque CREB3L4 (96% identical), rabbit CREB3L4 (86% identical), pig CREB3L4 (83% identical), dog CREB3L4 (77% identical), guinea pig CREB3L4 (76% identical), rat Creb3l4 (68% identical), mouse Creb3l4 (66% identical), tropical clawed frog creb3l4 (50% identical), Caenorhabditis elegans crh-2 (20% identical), Drosophila melanogaster CrebA (19% identical), Caenorhabditis elegans atf-6 (15% identical), and 3 more. Paralogues in human: CREB3L3 (36% identical), CREB3 (27% identical), CREB3L1 (25% identical), CREB3L2 (25% identical), ATF6 (20% identical), ATF6B (19% identical), CREB1 (14% identical), CREM (13% identical), ATF1 (12% identical).